RNU6-766P (RNA, U6 small nuclear 766, pseudogene)
Gene: Small nuclear RNA gene on chromosome 2 (168,606,390 to 168,606,496, reverse strand). Ensembl gene ENSG00000199348.
Homologues: Orthologues: chimpanzee U6 (98% identical), macaque U6 (93% identical). Paralogues in human: RNU6-21P (86% identical), RNU6-1024P (85% identical), RNU6-11P (85% identical), RNU6-1311P (85% identical), RNU6-15P (85% identical), RNU6-312P (85% identical), RNU6-37P (85% identical), RNU6-812P (85% identical), RNU6-188P (84% identical), RNU6-61P (84% identical), RNU6-86P (84% identical), RNU6-1 (83% identical), and 1287 more.